DDC (dopa decarboxylase)
Diseases named in the same sentence as DDC in open-access papers (continued):
Sharing a sentence is not in itself a finding about the gene and the disease.
autism (1 paper, 2015). Persistent deficits in social interaction and communication and interaction as well as a markedly restricted repertoire of activity and interest as well as repetitive patterns of behavior. "SNPs near the dopa decarboxylase gene (DDC) have been significantly associated with autism, and ddc knockdown in zebrafish results in a defective optokinetic response." (PMID 26092527, 2015).
Familial dysautonomia (1 paper, 2023). "A randomized, placebo-controlled, crossover phase 2 study of the effect of DOPA decarboxylase inhibitor carbidopa was conducted in 22 patients with familial dysautonomia." (PMID 37376074, 2023).
gestational diabetes (1 paper, 2023). Carbohydrate intolerance first diagnosed during pregnancy. "In this study, we investigated the effect of gestational diabetes on the expression of the Dopamine (DA) metabolism genes, tyrosine hydroxylase (TH), and dopa decarboxylase (DDC) in the olfactory bulb (OB) tissue of rats’ offspring." (PMID 37970447, 2023).
heroin dependence (1 paper, 2020). Physical and psychological dependence on the drug heroin. "This study aimed to identify the association between genetic polymorphisms of DA synthesis and metabolism genes, including tyrosine hydroxylase (TH), DOPA decarboxylase (DDC), solute carrier family 6 member 3 (SLC6A3) and DA beta-hydroxylase (DBH), with six important phenotypes of heroin dependence." (PMID 32736537, 2020).
hyperhomocysteinemia (1 paper, 2021). A serious metabolic condition caused by mutations in the MTHFR gene, medications, or nutritional deficiency. "Likewise, there is some consistent evidence in the heritability of impulse control disorder via Opioid Receptor Kappa 1 (OPRK1), 5-Hydroxytryptamine Receptor 2A (HTR2a) and Dopa decarboxylase (DDC) genotypes, and hyperhomocysteinemia via the Methylenetetrahydrofolate reductase (MTHFR) gene." (PMID 34281267, 2021).
Hyperphenylalaninemia (1 paper, 2016). "Hyperphenylalaninemia negatively influence dopamine utilization in the brain by competitive inhibition of the LNAA transporter and by reduced activity of DOPA decarboxylase." (PMID 27169416, 2016).
hypopharyngeal cancer (1 paper, 2025). Carcinoma, predominantly squamous cell, arising from the epithelial cells of the hypopharynx. "For hypopharyngeal cancer, GHRH, UCN3, LCE2B, DDC, and PCDHGC5 were upregulated." (PMID 40255484, 2025).
migraine (1 paper, 2011). "Risk variants and haplotypes in dopamine metabolism genes, DBH, DDC, MAOA, and SLC6A3, are reported to influence migraine risk, as are variants in the oestrogen receptor gene, ESR1." (PMID 22030984, 2011).
prostate adenocarcinoma (1 paper, 2020). "It has been reported that L-Dopa decarboxylase (DDC) is an AR coactivator that increases in expression with disease progression, and is co-expressed with AR in prostate adenocarcinoma cells, where it may enhance AR activity." (PMID 32404918, 2020).
α-thalassemia (1 paper, 2015). "The new candidates accounted for the remaining 19.2% of the explainable variation, with USP38 (8.1%), DDC (3.8%), FREM3 (3.0%), SDC1 (2.6%), and LOC727982 (1.7%) all accounting for more variation than ABO blood group and α-thalassemia but in aggregate less than the sickle HbAS polymorphism." (PMID 25805752, 2015).
tumor (17 papers, 2008 to 2025). "Increasing evidence indicates that L-dopa decarboxylase (DDC), which mediates aberrant amino acid metabolism, is significantly associated with tumor progression." (PMID 36544704, 2022). "The three most highly overexpressed genes: SCG3 (26.6 fold), SCG2 (15.3 fold) and DDC (9.6 fold), have previously been shown to be linked to NE tumour biology, thus confirming the reliability of our study design." (PMID 18827820, 2008). "Especially DDC is an enzyme that participates in the biosynthesis of biogenic amines that can facilitate or impede tumor progression, and hence a decrease in its mRNA levels can either have a favorable or adverse impact on cancer development." (PMID 33202911, 2020). "Even though expression of the dopamine synthesis genes TH and DDC can be identified in human tumors in the TCGA dataset, that information comes from bulk RNA-seq analysis of human tumor sections." (PMID 31822725, 2019). "Of the 32 patients, 28 showed increased DOPA decarboxylase activity in the primary tumour (sensitivity 88%, mean SUVmax 10.5)." (PMID 29766245, 2018). "[18F]DOPA PET/CT showed increased DOPA decarboxylase activity in the primary tumour of 28 patients with a maximum SUV (SUVmax)." (PMID 29766245, 2018). "In conclusion, incorporation of LeY enhanced uptake of liposomes by moDC and dDC which concomitantly increased activation of iNKT and CD8+ T-cells and thereby displayed potential as a tool for boosting anti-tumor responses." (PMID 32536918, 2020). "Compared with the normal group, the expression of DDC and SYT11 were remarkably up-regulated in the tumor group, while the expression of GCLM, PSMB7, TYRO3, and AGMAT were remarkably down-regulated in the tumor group." (PMID 38526709, 2025). "As expected, NB5t primary cells showed increased expression of mesenchymal genes (NT5E, ENG, ACTA2, MME, CD44, VIM or ALPL), while NB5t tumor sample expressed mostly neuronal genes (TH, ENO2, NCAM1, DDC or CHGB) reflecting the neuroblastic phenotype of stage 4/M NB tumors." (PMID 29163787, 2017). "The three most highly overexpressed genes in the NE vs the non-NE tumour cell group (SCG3, SCG2 and DDC), have all previously been described in the context of NE tumour biology, thus confirming the reliability of our study design." (PMID 18827820, 2008). "Dopamine is converted from tyrosine by enzymes tyrosine hydroxylase (TH) and dopa decarboxylase (DDC), and a previous study found that CCA tumors had higher expression levels of TH and DDC compared to normal liver tissues detected by immunohistochemistry using 48 CCA tumor tissues." (PMID 32069926, 2020).
cancer (11 papers, 2012 to 2025). A tumor composed of atypical neoplastic, often pleomorphic cells that invade other tissues. "DDC might function as a tumor suppressor protein and has been markedly linked to cancer progression and a worse prognosis in ccRCC." (PMID 36544704, 2022). "DDC expression has been investigated in several malignant tumors." (PMID 36544704, 2022). "Furthermore, the expression levels of cell proliferation and cytoskeleton-related proteins increased consistently during cancer development, such as ITGA4, DDC, and CPT1A; thus, they are potential diagnostic markers." (PMID 35958927, 2022). "Results indicated high expression of IL4I1, TDO2, NIT2, and IDO1, while IDO2, ADI1, DDC, HPD, BHMT2 exhibited low expression in most cancers." (PMID 38691253, 2024). "Moreover, DDC mRNA expression differs significantly in LSCC and TSCC patients, when classified according to the TNM stage or size of malignant tumors." (PMID 23083099, 2012).
genetic disorder (8 papers, 2019 to 2026). "AADC deficiency is a rare genetic disorder caused by mutations in the DDC (dopa decarboxylase) gene, leading to impaired production of the AADC enzyme." (PMID 41573373, 2026). "Aromatic l-amino acid decarboxylase (AADC) deficiency is a rare genetic disorder with heterogeneous phenotypic spectrum resulting from disease-causing variants in the dopa decarboxylase (DDC) gene." (PMID 31918669, 2020). "Aromatic l-amino acid decarboxylase (AADC) deficiency is a rare genetic disorder of neurotransmitter biosynthesis resulting from pathogenic variants in the dopa decarboxylase gene (OMIM #608,643) encoding the AADC enzyme (EC 4.1.1.28)." (PMID 38238766, 2024).
movement disorder (6 papers, 2018 to 2023). Neurological conditions resulting in abnormal voluntary or involuntary movement, which may impact the speed, fluency, quality and ease of movement. "Dopa decarboxylase (ddc) is involved in the synthesis of dopamine and serotonin which are related to movement disorder as well as a number of other functions." (PMID 31450778, 2019).
infection (4 papers, 2017 to 2025). The state of being infected such as from the introduction of a foreign agent such as serum, vaccine, antigenic substance or organism. "DV infection downregulated the mRNA levels of DDC, VMAT2 and MAO-B in IHH cells, indicating a generalized downregulation of the catecholamine biosynthesis/metabolism pathway." (PMID 35336971, 2022). "Infection did not alter levels of host tyrosine hydroxylase, DOPA decarboxylase (DDC), or the vesicular monoamine transporter (VMAT) in catecholaminergic cells, although DDC was observed in the parasitophorous vacuole in vitro and within tissue cysts in vivo." (PMID 28513566, 2017). "In contrast to NM larvae, and in the absence of infection, the M cuticle has higher basal levels of specific antifungal factors (apolipophorin III, gallerimycin, IMPI), antibacterial factors (gloverin) and general defenses (DOPA-decarboxylase, transferrin)." (PMID 31724467, 2019).
metabolic disorder (2 papers, 2016 to 2023). "Aromatic L-amino acid decarboxylase deficiency (AADCd) is a rare recessive metabolic disorder caused by pathogenic homozygous or compound heterozygous variants in the dopa decarboxylase (DDC) gene." (PMID 37761968, 2023).
DDC also shares sentences with these, for which no sentence is quoted: Parkinsonism (11 papers); neurological disorders (10); spinal muscular atrophy (8); developmental delay (6); Duchenne muscular dystrophy (5); epilepsy (4); neurodegenerative disease (4); autonomic dysfunction (3); Cognitive impairment (3); Dyskinesia (3); hemophilia (3); hemophilia A (3); Leber congenital amaurosis (3); lysosomal storage disorders (3); Retinal dystrophy (3); adrenoleukodystrophy (2); age-related macular degeneration (2); celiac disease (2); Cerebral ischemia (2); cerebral palsy (2); Huntington disease (2); insulinoma (2); medullary thyroid cancer (2); neurodevelopmental disorder (2); psychiatric disorder (2); achromatopsia (1); acromegaly (1); Addison's disease (1); Alzheimer disease (1); aminoacylase 1 deficiency (1).
A further 82 diseases each share a sentence with DDC in 1 paper.